CARS1 (cysteinyl-tRNA synthetase 1)
Description:
Catalyzes the ATP-dependent ligation of cysteine to tRNA(Cys).
Synonyms: CysRS; CARS; MCDDBH; MDBH; MGC:11246
Tractability: PROTAC: ubiquitination databases record sites on it; a small molecule that binds it is known.
Target class: Enzyme; Ligase
Gene: Protein-coding gene on chromosome 11 (3,000,922 to 3,057,613, reverse strand). Ensembl gene ENSG00000110619.
Subcellular location: Cytoplasm
Subcellular location (Human Protein Atlas): Cytosol
Pathways (Reactome):
Disease: Signaling by ALK fusions and activated point mutants
Metabolism of proteins: Cytosolic tRNA aminoacylation
Gene Ontology:
Molecular function: ATP binding; cysteine-tRNA ligase activity; identical protein binding; protein binding; tRNA binding; aminoacyl-tRNA ligase activity; nucleotide binding
Biological process: cysteinyl-tRNA aminoacylation; tRNA aminoacylation for protein translation
Cellular component: cytoplasm; cytosol
Genetic constraint (gnomAD): Loss-of-function variants: 40 observed, 91.12 expected, observed/expected ratio (o/e) 0.44, 90% interval 0.34 to 0.57. The upper end of that interval is the gene's LOEUF score, 0.57, which puts it in group 2 of 6, group 1 being the genes least tolerant of losing a copy. Missense variants: 884 observed, 986.79 expected, observed/expected ratio (o/e) 0.9, 90% interval 0.85 to 0.95. Synonymous variants: 385 observed, 381.52 expected, observed/expected ratio (o/e) 1.01, 90% interval 0.93 to 1.1.
Homologues: Orthologues: chimpanzee CARS1 (99% identical), macaque CARS1 (97% identical), mouse Cars1 (90% identical), guinea pig CARS1 (90% identical), rat Cars1 (89% identical), dog CARS1 (89% identical), pig CARS1 (79% identical), zebrafish cars1 (74% identical), tropical clawed frog cars1 (73% identical), Drosophila melanogaster CysRS (53% identical), Caenorhabditis elegans cars-1 (51% identical). Paralogues in human: CARS2 (26% identical).
Diseases named in the same sentence as CARS1 in open-access papers:
CARS1 is named in the same sentence as 32 diseases in open-access papers, as found by Europe PMC text mining. Sharing a sentence is not in itself a finding about the gene and the disease. The quoted sentences say what the papers report.
colon cancer (3 papers, 2021 to 2023). "constructed a novel prognostic signature involving CARS1, which effectively predicted the prognosis of colon cancer." (PMID 34249761, 2021). "We also performed immunohistochemistry against AKR1C1 and CARS1 in the colon cancer tissues and adjacent tissues." (PMID 34046350, 2021). "Immunohistochemistry was used to detect expression of AKR1C1 and CARS1 in colon cancer tissues and adjacent tissues." (PMID 34046350, 2021). "In the HPA database, we found that the expression of AKR1C1, ALOX12, and CARS1 in colon cancer tissue is higher than normal tissue and the expression of FDFT1 in colon cancer tissue is lower than normal tissue by immunohistochemistry, which is consistent with our results." (PMID 34046350, 2021).
esophageal adenocarcinoma (2 papers, 2022). A malignant tumor with glandular differentiation arising predominantly from Barrett mucosa in the lower third of the esophagus. "CARS1 was also recruited into a multigene signature to predict the prognosis in esophageal adenocarcinoma and hepatocellular carcinoma." (PMID 36313179, 2022). "Recent research has found that CARS1 is a new ferroptosis-related gene, predicting signature clinical prognosis in esophageal adenocarcinoma." (PMID 36213827, 2022).
inflammatory myofibroblastic tumor (1 paper, 2021). A multinodular intermediate fibroblastic neoplasm that arises from soft tissue or viscera, in children and young adults. "CARS1, cysteinyl-TRNA synthetase 1, is associated with tRNA function and contributes to the development of inflammatory myofibroblastic tumors and kidney cancer." (PMID 34336641, 2021).
liver cancer (1 paper, 2022). An epithelial or non-epithelial malignant neoplasm that arises from the liver. "More importantly, in the present study, the single-cell sequencing analysis results implied that SLC7A11, SLC1A5, CARS1, RPL8 and TFRC were not only upregulated in liver cancer cells but also expressed in immune cells." (PMID 35847985, 2022).
cancer (18 papers, 2012 to 2024). A tumor composed of atypical neoplastic, often pleomorphic cells that invade other tissues. "Based on the ESCC data from the TCGA cancer transcriptome database, CARS1 was remarkably associated with the prognosis (P = 0.027)." (PMID 36213827, 2022). "In addition, a previous a study suggested that enhanced expression of CARS1 was strongly correlated with unfavorable prognosis in various cancers and was associated with the expression of immune checkpoint genes, including PD-L1." (PMID 35847985, 2022). "Although ALK fusions with different partners are found in various cancers, the CARS1-ALK fusion has been reported only in IMT39." (PMID 35501376, 2022). "The CARS1 UNE-C1 domain shows a synergistic effect with cancer antigens and several immune checkpoint inhibitors in in vivo cancer models, suggesting further potential for the domain to be developed as an immunoadjuvant to activate antitumor immunity." (PMID 35501376, 2022). "Recent research indicated that CARS1 has prognostic values in predicting the overall survival of patients and targets ferroptosis as an alternative for therapy in several cancers." (PMID 36213827, 2022). "The sensing mechanism of cysteine by CARS1 is correlated with immune activation in cancer." (PMID 37258576, 2023). "CARS1 has been highly researched for its secretion from cancer cells when activated by TNF-alpha." (PMID 37258576, 2023). "Thus, CARS1 may be a potential novel prognostic biomarker and novel target for cancer immunotherapy." (PMID 35847985, 2022). "Meanwhile, four of the FRGs, ATP5MC3, HMGCR, CARS1, and PHKG2, are strongly related to the competitive endogenous RNA (ceRNA) network, which has become more and more popular in cancer research nowadays." (PMID 34868393, 2021). "Given the ability of UNE-C1, when produced by cancer cells, to induce ICD in those cells, it is plausible that CARS1 may also have a similar autocrine effect." (PMID 39669578, 2024).
tumor (12 papers, 2017 to 2025). "The tumor cell proliferation signature score was found to be positively correlated with CARS1 and FDFT1, indicating that the signature model has a high proliferation rate." (PMID 36582202, 2022). "Results showed the expression of AKR1C1 and CARS1 were different in tumor tissues and adjacent tissues." (PMID 34046350, 2021). "In our study, we investigated an aberrantly upregulated gene in ESCC tumor tissues CARS1 significantly inhibited cell proliferation, and the ability of migration and invasion promoted the relative level of MDA and ROS and decreased GPX4 expression level in two ESCC cell lines." (PMID 36213827, 2022). "In summary, five of the genes (CARS1, CHAC1, FANCD2, G6PD, and HMOX1) in the prognostic model have been reported to contribute to ferroptosis and to be upregulated in BC tumor tissue, in contrast to AIFM2." (PMID 36313179, 2022). "CARS1 may function in an antitumor capacity by promoting the ferroptosis process, regulating GPX4, reducing cell proliferation, migration, and tumor invasion." (PMID 41373571, 2025). "Cysteinyl-tRNA synthetase 1 (CARS1) belongs to a class 1 aminoacyl-tRNA synthetase and contains one of several posited around the imprinted gene domain, which is known as a critical gene region, and inhibited tumor growth." (PMID 36213827, 2022).
CARS1 also shares sentences with these, for which no sentence is quoted: Clear Cell Renal Cell Carcinoma (3 papers); infection (3); colorectal cancer (2); hepatocellular carcinoma (2); prostate carcinoma (2); alcohol dependence (1); Alzheimer disease (1); Anxiety (1); breast adenocarcinoma (1); breast carcinoma (1); breast tumors (1); coronary artery disease (1); developmental delay (1); fibrosarcoma (1); glioma (1); kidney cancer (1); lung carcinoma (1); medulloblastoma (1); melanoma (1); microcephaly (1); neuroblastoma (1); neurodegenerative disease (1); Pituitary adenoma (1); Silver-Russell syndrome (1); thyroid cancer (1); type 1 diabetes (1).